EGFR (epidermal growth factor receptor)
Diseases named in the same sentence as EGFR in open-access papers (continued):
Sharing a sentence is not in itself a finding about the gene and the disease.
glioblastoma (continued). "Together with the added advantage that CRISPRi with dCas9-KRAB does not involve direct modification of the DNA sequence but solely epigenomic editing, we focused our further investigation on the EGFR enhancer-repressed glioblastoma cell lines." (PMID 37803333, 2023). "These extracellular domain mutants keep EGFR in an active conformation and are reported in 24% of glioblastomas." (PMID 38201434, 2023). "For example, the guidelines suggest using mutations in IDH, the TERT promotor, and epidermal growth factor receptor (EGFR) as markers for glioblastoma (GBM)." (PMID 37241023, 2023). "Our results compare well with literature describing how and why the EGFR amplification in glioblastoma confers a unique biology." (PMID 36765632, 2023). "These two tumors had the combination of trisomy chromosome 7 and monosomy chromosome 10 along with genetic alterations typical of conventional IDH-wildtype glioblastoma (e.g., TERT promoter mutation, CDKN2A/B homozygous deletion, EGFR amplification)." (PMID 38079020, 2023). "eccDNA always reversibly drives the up-regulation or inhibition of mutant EGFR, thereby leading to a growth advantage in tumors with cells resistant to EGFR-targeted tyrosine kinase inhibitors after treatment, in glioblastoma cells." (PMID 39534571, 2023). "This ultimately contributes to a reduction of cell proliferation upon repression of the EGFR enhancers in glioblastoma." (PMID 37803333, 2023). "O’Rourke and colleagues, within a clinical trial testing an EGFR-based CAR T-cell therapy for glioblastoma, quantified cytokines in the peripheral blood of infused patients." (PMID 38136398, 2023). "Among primary glioblastoma, amplification of the epidermal growth factor receptor (EGFR) gene has emerged as both a key driving event and prognostic factor, occurring in roughly 57% of all primary adult glioblastomas." (PMID 36765632, 2023). "In U87.MGΔEGFR glioblastoma cells with constitutive expression of Epidermal growth factor receptor (EGFR) — a known regulator of PI3K/Akt signalling — PXDN was the most highly up-regulated gene." (PMID 37801286, 2023). "EGFR is a central signaling cascade for primary glioblastoma (36%) and is hardly found in secondary glioblastoma involved in controlling cell proliferation, survival, apoptosis, and overexpression of EGFR." (PMID 37675821, 2023). "We evaluated the therapeutic efficacy of GC1118, a novel anti‐epidermal growth factor receptor (EGFR) monoclonal antibody, in recurrent glioblastoma (GBM) patients with EGFR amplification." (PMID 37537946, 2023). "Although EGFR amplification is common in IDH-wildtype glioblastomas, immunohistochemistry for EGFR has poor specificity for detecting this molecular alteration." (PMID 37239289, 2023). "EGFRvIII, an oncogenic mutant of EGFR, is amplified in many glioblastoma multiforme (GBM) patients and is transferred between glioma cells via membranous microvesicles (so-called oncosomes)." (PMID 36835116, 2023). "The epidermal growth factor receptor (EGFR) is the most frequently altered gene in glioblastoma (GBM), which plays an important role in tumor development and anti-tumor immune response." (PMID 37601668, 2023). "EGFR amplification strongly correlates with increased EGFR expression and EGFR immunohistochemistry staining on tumor cells in glioblastoma." (PMID 38201434, 2023). "The aberrant activation of AKT due to EGFR dysregulation contributes to the uncontrolled growth and aggressiveness of glioblastoma cells." (PMID 37947601, 2023). "CED of cetuximab-conjugated iron oxide NPs demonstrated therapeutic effects in vivo for both EGFR-expressing glioblastoma (GBM) xenografts in mice and spontaneous intracranial gliomas in dogs." (PMID 37849659, 2023). "Depatuxizumab mafodotin (ABT-414) is an EGFR targeted ADC currently in phase 3 clinical trials for glioblastoma." (PMID 37720348, 2023).
glioblastoma (continued). "Our findings demonstrate how epigenomic perturbation of EGFR enhancers can ameliorate the aggressiveness of glioblastoma cells and enhance the efficacy of TMZ treatment." (PMID 37803333, 2023). "Amplification on chromosome 7, deletion on chromosome 10, amplification or mutation in EGFR, and deletion in the locus of Ink4a/ARF define classical glioblastoma." (PMID 38264122, 2023). "Multiple studies have shown EGFRvIII and EGFR amplification was the most common genetic alteration in glioblastoma, which was in accord with this study." (PMID 36622089, 2023). "ABT-414 uses the EGFR targeted mAb806 which has a higher affinity for EGFRvIII and greater efficacy against glioblastoma than cetuximab." (PMID 37720348, 2023). "In the context of glioblastoma, activation of Gcn2 by EGFR inhibitors was suggested to have a synergistic effect in reducing cancer cell survival and proliferation." (PMID 36898579, 2023). "EGFR is involved in several pathways that contribute to cell survival in glioblastoma, including the PI3k/Akt/mTOR and Ras/Raf/MAPK pathways, and can be induced by glutamatergic signaling." (PMID 36614191, 2023). "Human EGFR is highly expressed in glioblastoma-derived EVs, thus representing an optimal non-invasive candidate for the early detection of such intracranial tumour." (PMID 36683059, 2023). "Although it is known that c-Met crosstalk with EGFR, particularly EGFRvIII, drives glioblastoma pathogenesis and treatment resistance, clinical trials have yet to investigate the combination of EGFR inhibitors with c-Met inhibitors." (PMID 37857607, 2023). "This nanoparticle was employed for delivery of CPT-11 to U87 human primary glioblastoma cells with overexpressed EGFR on their surface." (PMID 37629816, 2023). "We compared gene expression in matched primary and recurrent glioblastoma samples, with a focus on those harbouring extra copies of the gene called EGFR (amplified samples)." (PMID 36765632, 2023). "To functionally demonstrate that the identified CEs act as EGFR enhancers in glioblastoma, we introduced targeted perturbations utilising both CRISPRi (dCas9-KRAB) and CRISPR/Cas9." (PMID 37803333, 2023). "All EGFR‐LFD‐positive glioblastoma cases were with EGFRvIII and co‐occurred with EGFR amplification." (PMID 36622089, 2023). "Glioblastoma has deletions in the EGFR extracellular domain (EGFRvIII); however, patients with GBM respond to temozolomide (chemotherapeutic) but not TKIs." (PMID 37508387, 2023). "For example, EGFR and two active enhancers were co-amplified and were maintained on circular ecDNA in glioblastoma samples from TCGA." (PMID 37448518, 2023). "Other mechanosensors promoting EMT via several pathways such as transient receptor potential melastatin 7 (TRPM7)/SOX4 in breast cancer, CXCR4/ubiquitin domain containing 1 (UBTD1)/YAP in hepatoma and EGFR in glioblastoma have been reported." (PMID 36906534, 2023). "The production of CSF-1 by glioblastoma cells attracts microglia and transforms them into a pro-tumorigenic phenotype, and microglia in turn stimulate glioblastoma cell invasion via EGFR activation." (PMID 37705736, 2023). "The uneven expression of EGFR, however, was proposed to be one of the contributing cause for the development of resistance to RTK-targeted therapy in glioblastoma." (PMID 37025487, 2023). "The elimination of the EGFRvIII-negative, EGFR-positive glioblastoma has been seen in a study on treatment with CART.BiTE." (PMID 36765623, 2023). "Genetic alterations common in glioblastoma, IDH-wildtype, were seen in two cases with available NGS data, including EGFR gene amplification, TERT promoter mutation, PTEN mutation, trisomy of chromosome 7, and monosomy of chromosome 10." (PMID 37686092, 2023).
glioblastoma (continued). "Taken together, our data highlights the functional importance of the EGFR regulatory genome in glioblastoma and it demonstrates the potential of enhancer modulation as a therapeutic strategy." (PMID 37803333, 2023). "EGFR has been reported as one of the targets of miR-7-5p in breast, ovarian and lung cancers and in glioblastoma." (PMID 37114127, 2023). "Of all 50 glioblastomas, the mean EGFR probe intensity levels (reflecting EGFR gene amplification) of amplified glioblastomas was 0.99, while the mean EGFR probe intensity levels of non-amplified glioblastomas was 0.04." (PMID 37444635, 2023). "In a previous study, KLHDC8A was highly expressed in glioblastoma cell lines that survived EGFR inhibitor treatment, and KLHDC8A compensated for the loss of a constitutively active variant of EGFR (EGFR VIII)." (PMID 36394953, 2023). "It has been previously reported that human cord blood MSCs downregulate PI3K/AKT, c-Myc/ERK and EGFR/c-Met activities, leading to a decrease in the invasion and migration potential of the glioblastoma cell line." (PMID 37298519, 2023). "EVs can help to confirm EGFR mutation status and make decisions about therapy because EGFRvIII-positive glioblastomas are over 50 times more likely to respond to EGFR inhibitor treatment." (PMID 36674900, 2023). "The nanoparticles were used for dual-targeted delivery of CPT-11 to U87 primary glioblastoma cells by actively targeting the overexpressed epidermal growth factor receptor on the surface of U87 cells, as well as by magnetic targeting." (PMID 37629816, 2023). "The gene of the Epidermal growth factor receptor (EGFR) is one of the most frequently altered genes in glioblastoma (GBM), with deletions of exons 2–7 (EGFRvIII) being amongst the most common genomic mutations." (PMID 36709315, 2023). "For instance, the liver was highly radioactive after treatment with [177Lu]Bz-DTPA-EGF for binding to EGFR for glioblastoma in mice." (PMID 37746282, 2023). "VP has also been shown to suppress expression of YAP/TAZ transcriptional targets (SOX2, C-MYC, and EGFR) in human patient-derived glioblastoma stem cells and confer significant survival benefit in the Drosophila GBM model." (PMID 36983079, 2023). "Antagonistic relationships between miR-218 and EGFR have also been demonstrated in glioblastoma and, indirectly, in osteosarcoma and esophageal squamous cell carcinoma." (PMID 37088795, 2023). "DHA C22:6n-3 is essential for the proliferation and self-renewal of glioblastoma cancer stem cells, which is related to the functioning of lipid rafts and EGFR." (PMID 37046844, 2023). "We first identified a panel of 10 conserved elements (CE1-CE10) as potential candidates to regulate the expression of EGFR in glioblastoma." (PMID 37803333, 2023). "We found that there are significant molecular differences in glioblastoma, depending on the EGFR amplification state." (PMID 37444635, 2023). "These bispecific monoclonal antibodies can link T cells to wild-type EGFR, overcoming the resistance of EGFRvIII heterogenous glioblastoma to EGFRvIII-specific CAR T cells." (PMID 36721153, 2023). "A direct link between PKM2 expression and EGFR activity was also established in human glioblastoma specimens." (PMID 36980255, 2023). "A few clinical trials are starting to assess the role of immunotherapy in the treatment of patients with glioblastoma, including some targeting specific molecular pathways such as EGFR." (PMID 36975416, 2023). "EGFRvIII-positive brain tumors were all glioblastoma IDH-wildtype, most with concurrent TERT promoter mutation (14 of 16), EGFR amplification (13 of 16), and EGFR mutation (8 of 16)." (PMID 38201434, 2023). "Previously, we generated a bivalent recombinant immunotoxin, hDT806, targeting EGFRvIII and overexpressed EGFR in cancers and demonstrated its high potency against glioblastoma cells with EGFR and EGFRvIII overexpression." (PMID 35453686, 2022).
glioblastoma (continued). "For example, glioblastoma harbors diverse EGFR genetic alterations, with the mutant EGFRvIII as a tumor-specific surface marker." (PMID 35453686, 2022). "The EGFR is an important signaling pathway that ectopic activation of this receptor has been extensively characterized in glioblastoma cells." (PMID 35804989, 2022). "While IDH wild-type LGG closely resembles glioblastoma (GBM) in both molecular signatures and clinical behavior, often including PTEN, EGFR and NF1 mutations." (PMID 36589241, 2022). "Conversely, the CD151-α3β1 complex can synergize with EGFR to enhance glioblastoma cell metastasis via the activation of FAKY397 and GTPase signaling pathways." (PMID 35524311, 2022). "It was demonstrated that synergistic use of OV-IL15C plus epidermal growth factor (EGFR)-CAR NK cells was able to suppress glioblastoma (GBM) cells and also enhanced the infiltration of NK and CD8+ T cells." (PMID 36434591, 2022). "The epidermal growth factor receptor (EGFR) is upregulated in glioblastoma, becoming an attractive therapeutic target." (PMID 35884571, 2022). "Polysomy of chromosome 7 and EGFR amplification on 7p are highly recurrent events in IDH-wild-type glioblastoma and were present in 66 and 48% of tumors, respectively." (PMID 35973991, 2022). "EGFR gene was duplicated in 40% of glioblastoma multiforme and increased its related glioma invasiveness and malignancy." (PMID 36536420, 2022). "EGFR gene copy number was first assessed by ddPCR in 15 IDH-wildtype glioblastomas with previously demonstrated EGFR amplification (samples 1–15)." (PMID 35361262, 2022). "EGFR amplification is common in adult IDH-WT glioblastoma, while PDGFRA activation is more common in pediatric tumors, including H3K27M-mutant diffuse midline gliomas." (PMID 35973991, 2022). "One particularly promising therapeutic target in glioblastoma is the epidermal growth factor receptor (EGFR)." (PMID 35456993, 2022). "We aimed to assess the tolerability and effectiveness of anti-EGFR immunoliposomes loaded with doxorubicin (anti-EGFR ILs-dox) in glioblastoma multiforme patients." (PMID 34998092, 2022). "Based on WHO 2021 classification and other previous reports has already established that Chr7 gain & Chr10 loss, TERT mutation along with EGFR expression and MGMT promoter methylation are the strongest predictor of survival in glioblastomas." (PMID 35144680, 2022). "In glioblastoma, CD73 is associated with EGFR amplification, astrocyte-like differentiation, and increased adenosine, and is linked to hypoxia." (PMID 35973991, 2022). "Compared with HA1800, the contact map of the EGFR-amplified glioblastoma-derived A172 cell line (referred to as A172 in the following context) showed a much “noisier” background (middle & bottom)." (PMID 35521558, 2022). "This information will inform the selection of EGFRvIII+ glioblastoma patients for inclusion in clinical studies designed to evaluate the efficacy of G17-6.02 in this EGFR genotype." (PMID 35456993, 2022). "Another differentially upregulated system in D10-017 compared to D317 is the insulin signaling pathway, which plays a role in glioblastoma survival and confers resistance to EGFR inhibitors." (PMID 35456993, 2022). "Brexpiprazole acts as chemosensitizer in pancreatic cancer and non-small cell lung cancer by downregulating expression of survivin which is an anti-apoptotic protein and thus it chemosensitizes the glioblastoma stem cells to osimertinib which is an EGFR-TKI." (PMID 35934727, 2022). "CX-4945, combined with gefitinib (an EGFR inhibitor), exerted a strong antiviability effect on glioblastoma cells in vitro." (PMID 35214064, 2022). "To explore the alteration of 3D genomic structure at loop level in EGFR-amplified glioblastoma, we analyzed the Hi-C data from both HA1800 and A172 cell lines." (PMID 35521558, 2022). "The correlation established between EGFR and PD-1 in glioblastoma is affiliated to the expanded rate of EGFR amplification due to the expression of PD-1." (PMID 35806478, 2022).
glioblastoma (continued). "This disordered 3D genomic map and multi-omics data of malignant EGFR-amplified glioblastoma provide a resource for future interrogation of the relationship between epigenetic and genetic in tumorigenesis." (PMID 35521558, 2022). "EGFR mutants with C-terminal deletions, EGFRvIVa and EGFRvVIb, have been found in human glioblastoma multiforme." (PMID 36531494, 2022). "In glioblastomas, EGFR is expressed on cancer cells, healthy brain cells, and other tissues, making healthy cell killing a greater risk of morbidity and mortality." (PMID 35903149, 2022). "Patients with IDH1/2-wildtype glioblastomas harboring CDKN2B, EGFR, and TERT promoter mutations who underwent GTR were associated with improved OS when compared to other EOR in the FDR-adjusted analysis." (PMID 35156038, 2022). "Glioblastoma must have wild-type IDH gene and some characteristics, such as TERT promoter mutation, EGFR gene amplification, microvascular proliferation, among others." (PMID 35804976, 2022). "This study also evaluated safety data of the application of anti-EGFR ILs-dox in patients with relapsed glioblastoma." (PMID 34998092, 2022). "Approximately 50–60% of primary glioblastomas exhibit genetic changes in EGFR, including amplifications, rearrangements, alternative splicing, and mutations." (PMID 36135196, 2022). "It differs from primary IDH wild-type glioblastoma by a slightly higher PTEN mutation rate and infrequent EGFR alterations." (PMID 35932030, 2022). "Structure variations (SVs) had a dramatic impact on the chromatin conformation of EGFR-amplified glioblastoma-derived tumor cells." (PMID 35521558, 2022). "High frequencies of epidermal growth factor receptor (EGFR) amplification, TERT promoter mutation, and PTEN loss are characteristic in idh wild-type glioblastomas." (PMID 36776374, 2022). "For example, higher invasion was observed when glioblastoma cells expressed EGFR and responded to EGF secretion from microglia." (PMID 35053605, 2022). "To expand on these experiments, we also performed a similar xenograft experiment in which wild-type or hinge modified sdCAR-T cells were delivered intratumorally in the relatively more aggressive EGFR-high U87-vIII glioblastoma xenograft model." (PMID 35935988, 2022). "For example, in glioblastoma, the receptor tyrosine kinase signalling pathway can be altered by disruption of the EGFR oncogene, either via gene fusion (EGFRvIII fusion) or gene dosage increase (EGFR amplification), caused by either simple or complex SVs." (PMID 35355264, 2022). "In a large independent cohort of glioblastoma from the TCGA, we also found a statistically significant positive correlation between EGFR and CD73 expression (p = 0.039)." (PMID 35973991, 2022). "Erlotinib is an inhibitor of EGFR and has been approved to treat non-small cell lung and pancreatic cancers and was shown to exert multifarious antineoplastic effects in glioblastoma in preclinical studies." (PMID 36532035, 2022). "It was also shown that constitutively active EGFR signaling drives lipid synthesis in glioblastoma models through a PI3K/Akt/SREBP-1 signaling axis." (PMID 36230918, 2022). "The high level of intra-tumoral heterogeneity within glioblastomas has contributed to the failure of EGFR-targeted therapies." (PMID 36199696, 2022). "In glioblastoma, EGFR signaling induces GBP-1, which promotes cell invasion in vitro and in vivo and cell proliferation in vivo." (PMID 35681772, 2022). "EGFR is overexpressed in nearly 60% of glioblastoma tumors, often the consequence of gene amplification (in 40% of these tumors) or the common EGFRvIII deletion (in 25% of these tumors), and it is considered a poor prognostic factor." (PMID 35743016, 2022). "The presence of one or more of the following three genetic parameters EGFR gene amplification, TERT promoter mutation and 7+/10–, is required to upgrade astrocytoma, IDH-wildtype to glioblastoma, IDH-wildtype." (PMID 36425564, 2022).